BRCA1 (BRCA1 DNA repair associated)
Diseases named in the same sentence as BRCA1 in open-access papers (continued):
Sharing a sentence is not in itself a finding about the gene and the disease.
tumor (continued). "Since inhibition of the AKT/mTOR pathway leads to downregulation of BRCA1/2 and homologous recombination and olaparib activates AKT/mTOR signaling, the combination of olaparib and ONC206 may have a synergistic effect in inhibiting tumor growth in EC via dual inhibition of the AKT/mTOR pathway." (PMID 37069726, 2023). "Of the 331 tumor samples analyzed from the non-gBRCAm cohort, 283 (85.5%, 283/331) were BRCA wild type (BRCAwt) with no detectable deleterious or suspected deleterious mutation in BRCA1/2, and 48 (14.5%, 48/331) carried deleterious or suspected deleterious somatic BRCA1/2 mutations (sBRCAm)." (PMID 36970052, 2022). "On the other hand, in BRCA1-mut women, lacking BRCA1-mediated repression of ERα transcriptional activity, high ERα levels, not inhibited by ERβ5, result in increased ligand-dependent transcriptional activity which may, in turn, stimulate tumour growth." (PMID 36230510, 2022). "Based on this evidence, one could propose that because RAD51 possesses both BRCA1/2/PALB2-dependent and BRCA1/2/PALB2-independent functions during replication, its inactivation would be more toxic than that of one of the loading factors, thus impairing the proliferation of tumour cells." (PMID 34316706, 2021). "Although we did observe a more mesenchymal sub-population in BRCA1-null tumors and the process of EMT has been shown to confer stem-like properties, it would be interesting to identify other potential factors that may regulate tumor cell plasticity in some of the other tumor sub-populations." (PMID 32840210, 2020). "In addition, the tumor was not hypermethylated, and expressed BRCA1 on the IHC evaluation." (PMID 32235500, 2020). "In the present study, we have not investigated if that tumor suppressor role for FL BARD1 is dependent from BRCA1, but we should consider that FL BARD1 might act in additional pathways involved in carcinogenesis through additional binding partners that remain not investigated." (PMID 32047556, 2020). "Therefore, regarding both tumor and germline BRCA1/2 testing, we can agree as NGS alone is not enough: in fact, many strategies should be used to approach to BRCA testing, particularly due to the complexity of these two genes along with their ability to rearrange." (PMID 29731958, 2018). "Therefore, if NGS-based assays are to be used on tumour tissue to determine eligibility for PARP inhibitors, it may be appropriate to consider screening for biallelic LOF (i.e. homozygosity) in RAD51C and RAD51D as well as BRCA1 and BRCA2." (PMID 29464354, 2018). "However, upon energy stress, lncRNA NBR2 (neighbor of BRCA1 gene 2) could promote AMP-activated protein kinase (AMPK) activity through interacting with AMPK, leading to a depressed autophagy response and increased tumor development." (PMID 28293170, 2017). "Interestingly, from these 17 significant pairs (adjusted p-value ≤ 0.05) several downregulated tumour-suppressor miRNAs (e.g., miR-let-7c, miR-139, miR-145 or miR-195) appeared to regulate oncogenic genes related to the cell cycle and DDR pathways (BUB1B, AURKA, BIRC5, CENPK, BRCA1 and CHEK1)." (PMID 28387377, 2017). "However, considering BRCA1 and BRCA2 were thought be tumor suppressor proteins, it is alarming that the inhibitory effect of curcumin on the expression of BRCA1 and BRCA2 in T241 cells might lead to tumor progression." (PMID 29255221, 2017).
tumor (continued). "So the BDS would range between zero “0” on the one extreme, which would indicate absolute BRCA1 deficiency since the tumor was categorized to be deficient in all three measures, and a maximum BDS of “3” which indicated no repression and complete adequacy in all measures of BRCA1." (PMID 27077368, 2016). "Thus, the CD44+/24–/low population abundance could be independent of BRCA1 expression and dependent on the tumor sub-type." (PMID 27229859, 2016). "However, BRCA1 and BRCA2 are members of a complex network of proteins involved in DNA repair and genomic stability, suggesting their role could extend beyond regulation of neoplasia." (PMID 22809218, 2012). "In addition to BRCA1 (93.7 ± 6.6% vs 72.8 ± 20.7%, P = 0.0044), significant differences in tumor volume were observed between positive and negative γH2AX (78.4 ± 17.4% vs 65.6 ± 26.8%, P = 0.0429) and Rad51 baseline foci groups (78.1 ± 18.9% vs 63.6 ± 24.4%, P = 0.0351)." (PMID 20205718, 2010). "Similarly, Brca1 and Brca2 heterozygosity did not affect tumor formation induced by the Wnt-1 transgene, and partial deletion of the INK4a locus that encodes both p16INK4a and p19ARF did not result in increased DMBA-induced tumor formation." (PMID 19267898, 2009). "Furthermore, all five tumours showed absent or markedly reduced BRCA1 protein expression." (PMID 16846527, 2006). "As BRCA1-related tumours exhibit poor prognostic characteristics (negative oestrogen receptor status and high grade) and have often been shown to be associated with impaired survival rates, this could explain the negative impact of strong family history in the subgroup of very young women." (PMID 16404417, 2006). "This study shows that, in a real-world clinical setting with a nationwide implemented tumor-first testing workflow, approximately one out of three EOC patients did not receive the recommended BRCA1/2 testing." (PMID 40323485, 2025). "miR-675 expression correlates with age, menopausal status, tumor size, histology, clinical stages, ER status, HER2 status, non-TNBC, BRCA1 status, and BRCA2 status (P<0.05), but not with other clinical pathological parameters." (PMID 39267845, 2024). "Additionally, we observed a negative impact of BRCA1 on immune cells infiltration, indicating that the presence of this gene may impair the body’s ability to mount an effective immune response against the tumor." (PMID 38224491, 2024). "A high HRD score has been shown to be predictive of clinical benefit with PARP inhibitor therapy, independent of BRCA1/2 status in ovarian cancer, but its predictive value of sensitivity to PARP inhibitors or platinum in other tumor types is still unclear." (PMID 36964191, 2023). "In the present data set, however, the number of patients carrying BRCA1 WBC and tumor methylation in concert does not allow for assessment of such a potential correlation." (PMID 38053165, 2023). "Analyzing BRCA1 methylation in matched blood and tumor tissue of patients with both TNBC and non-TNBC, we found a strong correlation between tumor tissue and WBC BRCA1 methylation in TNBC and tumors revealing a low ER expression (1–9%)." (PMID 38053165, 2023).
tumor (continued). "As an example, patient 21556, who carries a germline mutation in BRCA1, could be potentially eligible for PARPi therapy, but the targeted analysis of cfDNA at the time of diagnosis revealed the presence of two pathogenic variants in the TP53BP1 gene not detected in the tumor lesions analyzed." (PMID 35954363, 2022). "However, recent evidence has emerged from WGS that indicates that tumours with large heterozygous deletions spanning the length of both BRCA1 and BRCA2, in the absence of SNVs/indels, are also more likely to be HR‐deficient and may also benefit from PARP inhibitors." (PMID 35355264, 2022). "Importantly, comparing 4 BRCA1 mutated (HCC1739, MDA-MB-436, Sum1315MO2, and Sum149PT) and 4 BRCA1 wild-type (BT549, MDA-MB-231, MDA-MB-436, and CAL15) TNBC cell lines, ARN3261 significantly inhibited tumor cell growth in all 8 cell lines tested regardless of BRCA1 mutation status." (PMID 35642638, 2022). "Because homologous recombination (HR) repair is abrogated in the absence of BRCA1 or BRCA2, these lesions are specifically lethal to tumour cells, but not to the healthy tissue." (PMID 35107878, 2022). "First, we evaluate whether tumor size, categorized as pT1a (0.1–0.5 cm), pT1b (> 0.5–1.0 cm), and pT1c (> 1.0–2.0 cm) according to the TNM classification of malignant tumors, UICC (TNM), is a good prognostic factor of survival in pT1N0 BRCA1/2-associated BC patients who did not receive chemotherapy." (PMID 35507134, 2022). "Importantly, almost half (11/23) of individuals with BRCA1/2 PV in their tumour could not correctly recall their genetic testing result, which likely translates to an inaccurate evaluation of the psychological effect of receiving a positive BRCA1/2 tumour genetic testing result." (PMID 35418215, 2022). "In tumor biopsies from non-responders, GPR110 and TNIK were significantly upregulated, while WDR4 and BRCA1 were significantly downregulated, as compared to those of responders (p < 0.05)." (PMID 34572869, 2021). "While studies have not examined the prognostic ramifications of tumor-cell PDGF/PDGFRβ expression, our results here using mouse and human tumors indicate a high likelihood that tumor cell PDGFRβ staining might provide prognostic information in BRCA1/INK4-RB-deficient tumors." (PMID 33478572, 2021). "However, it remains obscure whether the interaction of BRCA1 with Senataxin or COBRA1 implies a different mechanism by which BRCA1 recognises R-loops in the genome and how this could be acting in its regulation for the maintenance of the genetic integrity and the inhibition of tumour formation." (PMID 33755171, 2021). "Somatic BRCA1 or BRCA2 mutation carriers were identified with bidirectional sequencing of DNA from archived tumor tissue, if the test could not be performed due to technical reasons from tumor cells, the sequencing was done from peripheral blood cells to identify germline mutation carriers." (PMID 33478135, 2021). "While BRCA1 and BRIP1 work as tumour suppressor genes, when BRIP1 fails to bind BRCA1 in certain conditions, cells become sensitive to different genotoxic stresses with aberrant homologous DNA repair function." (PMID 32888398, 2020). "Although BRIP1 interacts with BRCA1 to regulate cell cycle and DNA repair mechanisms, the role of BRIP1 in mediating tumour growth and progression has not been examined yet." (PMID 32888398, 2020). "A lack of association between BRCA1 mutations and PCa grade is in line with published data, and the higher SIR for GS ≤ 6 disease might reflect a higher propensity for diagnosing indolent low-grade tumours that would not have been detected in the absence of the discovery of a deleterious mutation." (PMID 31495749, 2020). "In the SCAN-B cohort, there was no statistical difference in tumor cell content estimated by WGS between hypermethylated and BRCA1-null cases (t-test, p = 0.47), suggesting that nonmalignant infiltration should not affect group-level conclusions." (PMID 32719340, 2020).
tumor (continued). "Among patients testing positive for BRCA1 methylation in WBC, 62% were methylation positive in the tumor tissue, contrasting 12% for patients testing negative for WBC BRCA1 methylation." (PMID 31225507, 2019). "We examined BRCA1 mutant PDX tumors and discovered that more than 80% of tumor cells expressed a high level of VIM without treatment." (PMID 29996906, 2018). "BRCA1 tumours were largely triple negative and less commonly HER2 positive, whereas BRCA2 tumours were more likely to be hormone receptor positive." (PMID 35693198, 2018). "Eight patients, who were BRCA1 and BRCA2 wild type carriers with luminal HER2 negative tumors, had their tumor and normal exomes sequenced." (PMID 29854292, 2018). "Assessment of individual tumor‐level data indicates that HR alterations are not mutually exclusive, and the most frequently altered HR gene is NBN (22%), while BRCA1 and BRCA2 are altered in ~ 7 and 8% of these tumors, respectively." (PMID 30467127, 2018). "In another study, although several genes or spliced transcripts were identified as differentially expressed in familial cases, they did not allow clusterization of BRCA1, BRCA2 and BRCAX tumor tissues." (PMID 29108258, 2017). "However the BRCA1 murine model, BRCA1-I26A, in which BRCA1 interaction with E2 Ub conjugating enzymes is reduced, is viable and not tumor prone, and if the fidelity of HR promoted by other regions of BRCA1 remains high this may explain why tumor development is stymied." (PMID 28032817, 2017). "Cells carrying intact Brca1 (Brca1+/+) showed no sensitivity to PDS or olaparib, while cells established from a Brca1−/− tumor were sensitive to both drugs, as determined in viability and clonogenic assays." (PMID 26748828, 2016). "As expected, the rates of liquid plasma-induced cell death in the coculture system (which mimics tumor heterogeneity) were comparable to the death rates under the single culture conditions for ATM and BRCA1 positive and negative cells." (PMID 27364630, 2016). "The author reported that prolonged survival was observed in BRCA1- and RRM1-negative tumours but not among patients with BRCA1- and RRM1-positive tumours." (PMID 26663950, 2015). "In contrast, the addition of BRCA1-related parameters (mRNA, protein and BARD1 ligated to BRCA1) to the same three conventional prognostic factors (node invasion, tumor size and CK5/6 expression) did not improve the model performances." (PMID 26490435, 2015). "In general, the carriers of BRCA1 and BRCA2 show higher tumor stage, grade and ER negative tumors, and more metastasis to neighbor vessels relative to those who harbor other gene mutations." (PMID 24312913, 2013). "So, in this study, we use RT-PCR to examine the expression of ERCC1, BAG-1, BRCA1, RRM1 and TUBB3 in tumor samples from patients with resected NSCLC not receiving adjuvant chemotherapy." (PMID 22439756, 2012). "Alternatively, it is possible that the dramatic increase in AKT and survivin expression and/or activation in BRCA1-IRIS-induced tumors and not RasV12-induced tumors generate tumor cells that are more aggressive." (PMID 22511931, 2012). "A correlation study of the methylation proportion of DNA in serum versus cancerous and normal breast tissue revealed a correlation between tumor tissue and serum for BMP6, BRCA1, CST6, GSTP1, P16 and TIMP3 genes but not with the matched normal tissue." (PMID 21283676, 2011). "The fraction of losses in the BRCA1 and BRCA2 tumor groups were not significantly different from The fraction of losses found in the sporadic control group." (PMID 20735817, 2010). "Here, we have profiled and examined the patterns of genomic alterations in familial BRCA1 and BRCA2 tumours in the context of sporadic tumours with and without epigenetic silencing of the BRCA1 gene." (PMID 19589159, 2009). "We have previously shown that inactivation of Brca1 alone in the OSE resulted in an increase in the number of preneoplastic changes in the OSE after 240 days, but no tumor formation." (PMID 20046869, 2009).
tumor (continued). "We inactivated Brca1 in the murine OSE which resulted in the increased accumulation of premalignant changes, although no tumor formation was observed after one year." (PMID 20046869, 2009). "Full-length BRCA1 cDNA transfection of BRCA1-defective HCC1937 cells led to the reconstituted expression of BRCA1 protein in HCC1937/WTBRCA1-derived cell clone, but did not reduce tumour cell growth in soft agar." (PMID 12698198, 2003). "These regulatory mechanisms, when considered alongside prior findings and hypotheses, may help explain why BRCA1 and BRCA2 proteins do not exhibit tumor-suppressive functions in most cell types." (PMID 40841483, 2026). "Furthermore, the tumor tissue for molecular testing was limited with only a single CRC with sufficient DNA for WES and therefore, confirmation that HRD associated mutational signatures were the dominant mutational process in the other CRCs from BRCA1 carriers could not be determined." (PMID 38063999, 2024). "Notably, in addition to the 20% of TNBC found to harbor constitutional BRCA1 promoter methylation, we found another 10% of TNBC to harbor BRCA1 epimutations in their tumor tissue but not WBC." (PMID 40225940, 2024). "In sporadic gastric cancer patients after receiving postoperative adjuvant chemotherapy, BRCA1/BRCA2 expression assessed using IHC and mRNA tests displayed a correlation between BRCA2-elevated expression with advanced tumour stage but not disease-free and overall survival." (PMID 39080120, 2024). "Although there was not statistically differences between BRCA1 c.5309G>T carriers group and BRCA2 c.1310_1313delAAGA carriers group in terms of tumor laterality, histopathological subtype, tumor grade, RE and RP expression, we detected proportional differences between patients groups." (PMID 37055759, 2023). "Among 17 patients carrying concordant BRCA1 methylation in WBC and tumor tissue, SNP rs799905 genotype information was lacking and/or could not be linked to methylation in two patients." (PMID 38053165, 2023). "However, the deletion of BECN1 in human cancers and the deletion of the breast cancer 1 (BRCA1) gene cannot be disassociated, which indicates that BECN1 is not a tumor suppressor in most human cancers." (PMID 36197606, 2022). "Furthermore, in the present study, although the M2 macrophage polarization and expression of VEGR, TNF-α, BRCA1, and HER2 showed differences among the different ERα+/ERα− ratio groups, the tumor size was not significantly different." (PMID 36118080, 2022). "Rapidly proliferating tumor cells and hemopoietic stem cells with a higher HRD score were more easily targeted by DNA-damaging agents than the relatively quiescent somatic cells, regardless of BRCA1/2 expression." (PMID 34869593, 2021). "Although the BRCA1–CtIP complex has been shown to be critical for the HR pathway in chicken DT40 cells, another research reported this interaction is not necessary for resection-mediated DNA repair or tumor suppression in mammalian cells." (PMID 33013205, 2020). "Since BRCA1 protein expression is not directly correlated to its mRNA level in NPC cell lines and primary tumours, we postulated that BRCA1 expression in NPCs may be regulated in the post‐transcriptional level, likely due to the miRNAs derived from EBV." (PMID 33074587, 2020).